IRAK2 (interleukin 1 receptor associated kinase 2)
Description:
Binds to the IL-1 type I receptor following IL-1 engagement, triggering intracellular signaling cascades leading to transcriptional up-regulation and mRNA stabilization.
Synonyms: IRAK-2
Tractability: Small molecule: it belongs to a druggable protein family. Antibody: its Gene Ontology location is reachable by antibodies, with high confidence. PROTAC: ubiquitination databases record sites on it; a small molecule that binds it is known.
Gene: Protein-coding gene on chromosome 3 (10,164,863 to 10,243,756, forward strand). Ensembl gene ENSG00000134070.
Subcellular location (Human Protein Atlas): Vesicles
Pathways (Reactome):
Immune System: IRAK2 mediated activation of TAK1 complex; IRAK2 mediated activation of TAK1 complex upon TLR7/8 or 9 stimulation; Interleukin-1 signaling; JNK (c-Jun kinases) phosphorylation and activation mediated by activated human TAK1; MyD88 cascade initiated on plasma membrane; MyD88 dependent cascade initiated on endosome; MyD88:MAL(TIRAP) cascade initiated on plasma membrane; NOD1/2 Signaling Pathway; TAK1-dependent IKK and NF-kappa-B activation; TRAF6 mediated induction of NFkB and MAP kinases upon TLR7/8 or 9 activation; TRAF6-mediated induction of TAK1 complex within TLR4 complex; activated TAK1 mediates p38 MAPK activation
Disease: SARS-CoV-1 activates/modulates innate immune responses; SARS-CoV-2 activates/modulates innate and adaptive immune responses
Gene Ontology:
Molecular function: molecular adaptor activity; protein binding; protein heterodimerization activity; protein homodimerization activity; signaling adaptor activity; ATP binding; identical protein binding; protein kinase activity
Biological process: canonical NF-kappaB signal transduction; interleukin-1-mediated signaling pathway; negative regulation of canonical NF-kappaB signal transduction; regulation of cytokine-mediated signaling pathway; response to interleukin-1; toll-like receptor 4 signaling pathway; inflammatory response; intracellular signal transduction; lipopolysaccharide-mediated signaling pathway; MyD88-dependent toll-like receptor signaling pathway; NLRP3 inflammasome complex assembly; positive regulation of canonical NF-kappaB signal transduction; protein phosphorylation; regulation of MAP kinase activity; Toll signaling pathway; toll-like receptor signaling pathway; signal transduction
Cellular component: cytoplasm; cytosol; endosome membrane; plasma membrane; serine/threonine protein kinase complex
Genetic constraint (gnomAD): Loss-of-function variants: 49 observed, 64.6 expected, observed/expected ratio (o/e) 0.76, 90% interval 0.6 to 0.96. The upper end of that interval is the gene's LOEUF score, 0.96, which puts it in group 4 of 6, group 1 being the genes least tolerant of losing a copy. Missense variants: 759 observed, 784.16 expected, observed/expected ratio (o/e) 0.97, 90% interval 0.91 to 1.03. Synonymous variants: 277 observed, 309.76 expected, observed/expected ratio (o/e) 0.89, 90% interval 0.81 to 0.99.
Homologues: Orthologues: chimpanzee IRAK2 (99% identical), macaque IRAK2 (83% identical), dog IRAK2 (80% identical), pig IRAK2 (78% identical), rat Irak2 (71% identical), mouse Irak2 (70% identical), rabbit IRAK2 (67% identical), guinea pig IRAK2 (63% identical), tropical clawed frog irak2 (37% identical), Drosophila melanogaster pll (16% identical), Caenorhabditis elegans pik-1 (16% identical), Drosophila melanogaster Haspin (7% identical), and 3 more. Paralogues in human: IRAK1 (28% identical), IRAK3 (20% identical), IRAK4 (19% identical), HASPIN (12% identical).
Diseases named in the same sentence as IRAK2 in open-access papers:
IRAK2 is named in the same sentence as 73 diseases in open-access papers, as found by Europe PMC text mining. Sharing a sentence is not in itself a finding about the gene and the disease. The quoted sentences say what the papers report.
asthma (6 papers, 2011 to 2023). "Furthermore, we found that the expression of some molecules such as CD14, TLR5, TLR6, TLR8, TREM-1, but also IRAK-1 and IRAK-2 genes was significantly negatively associated with total serum IgE, atopic sensitization, or asthma." (PMID 24603716, 2014). "Immune transcriptome analysis of LNR125 treated BECs from individuals with asthma indicated that blocking IL-25 restored antiviral immunity with evidence of upregulation of ISGs, such as IRF7 and TBK1 and interleukin-1 receptor-associated kinase 2 (IRAK2)." (PMID 35508632, 2022). "IRAK-1, IRAK-2, and RIPK1 were the only molecules, whose gene expression was associated to both farming environment and asthma." (PMID 24603716, 2014). "CXCL10 was upregulated in asthma and LCP1, CCR1, PRKCB, IRAK2, LILRA1, and ZEB1 were significantly upregulated in COPD patients." (PMID 36829591, 2023). "Although we could show that the farm-environmental mediated up-regulation in IRAK-1, IRAK-2, and RIPK1 contributed partially to their reduced incidence of asthma." (PMID 24603716, 2014).
viral infection (6 papers, 2012 to 2024). "During viral infection, miR-146a-5p suppresses the production of type-I interferon by targeting not only IRAK2, TRAF6, and IRAK1 but also STAT-1 and IRF-5." (PMID 38787176, 2024). "IRAK2 has been primarily demonstrated to be a target of miR146a-5p in the context of viral infection leading to inhibition of RIG-1 mediated type I interferon production." (PMID 37319241, 2023). "TRAF6, IRAK1 and IRAK2 play major roles in regulation of immune responses during viral infections." (PMID 25083878, 2014). "For example, it has been shown that miR-146a is upregulated during viral infection in macrophages and acts as a negative regulator of the retinoic acid-inducible gene I (RIG-I)-like helicases by targeting not only IRAK1 but also TRAF6 and IRAK2." (PMID 23028621, 2012).
diabetes (4 papers, 2013 to 2026). "Because ER stress has been implicated in the pathogenesis of multiple diseases, including neurodegeneration, diabetes, IBD, and cancer, IRAK2 represents a potential new drug target." (PMID 23724040, 2013).
diabetic cardiomyopathy (4 papers, 2015 to 2024). Diabetic cardiomyopathy is a disorder of the heart muscle in people with diabetes. "Meanwhile, adipsin mitigates mitochondrial damage and enhances β-oxidation of fatty acid in diabetic cardiomyopathy through its interaction with Irak2 and impediment of Irak2 mitochondrial translocation." (PMID 39538244, 2024).
lung cancer (4 papers, 2015 to 2022). A malignant neoplasm involving the lung. "IRAK2 is associated with lung cancer and a high eosinophil count." (PMID 36194576, 2022). "In PhenoScanner, 6 out of 12 hub genes (IRAK2, MECOM, ASB4, CDC42BPA, DPF3 and TMEM67) have revealed an association with lung related traits and lung cancer." (PMID 36194576, 2022). "IRAK2 promotes the EMT phenotype through miR-373 regulation in non–small cell lung cancer cells." (PMID 34455105, 2021). "The link between IRAK-1 expression and obesity-associated meta-inflammation is also supported by the relationship of IRAK-1 or IRAK-2 with other inflammatory conditions such as lung cancer, systemic lupus erythematosus, Vogt-Koyanagi-Harada (VKH) disease, and Alzheimer’s disease." (PMID 26312071, 2015). "Interestingly, pathways enriched by MECOM and IRAK2 were involved in lung cancer development." (PMID 36194576, 2022). "Out of 12 hub genes, only 4 (IRAK2, SREK1, C1QTNF2 and DDX3Y) have shown significant gene expression in lung cancer compared to the normal tissues." (PMID 36194576, 2022). "Medium staining detection of CDC42BPA and IRAK2 were found in both normal and cancer lung tissue in addition to SREK1 and C1QTNF2 which was observed in medium in normal tissue but higher in lung cancer tissue." (PMID 36194576, 2022).
glioblastoma (3 papers, 2012 to 2014). The most malignant astrocytic tumor (WHO grade IV). "In addition, the expression of gene coding for interlukin-1 receptor-associated kinase 2 (IRAK2) proteins which activates nuclear factor kappa-B (NF-kB) was up-regulated in glioblastoma cells, KNS60, and down-regulated in medulloblastoma cells, ONS76." (PMID 25307264, 2014). "Anand Iyer, et.al 2012 reported that miR-146a mimics can significantly reduce the mRNA expression levels of TRAF6, IRAK1 and IRAK2 protein levels in IL-1β stimulated human astrocytes and glioblastoma cell line." (PMID 25083878, 2014). "In both the glioblastoma cell line and human astrocytes transfection with miR-146a mimic, significantly reduced IRAK-1, IRAK-2 and TRAF-6 mRNA and IRAK-1 protein after stimulation with IL-1β." (PMID 23028621, 2012).
tuberculosis (3 papers, 2017 to 2025). A chronic, recurrent infection caused by the bacterium Mycobacterium tuberculosis. "‘Tuberculosis’ KEGG pathway map comprised five signal transduction mediators, Irak2, Jak2, Malt1, Ripk2, and Src, regulated by induced enhancers." (PMID 30669987, 2019).
breast carcinoma (2 papers, 2015 to 2023). "Moreover, IRAK2 downregulation was previously associated with increased apoptosis in canine breast cancer." (PMID 36768848, 2023).
COVID-19 (2 papers, 2021 to 2023). A disease caused by infection with severe acute respiratory syndrome coronavirus 2. "Interleukin 1 receptor-associated kinase 2 (IRAK2), upregulated in both COVID-19 and ICM, was associated with the upregulation of the FCER1 and TP63 pathways, both of which are associated with inflammation and immune activation (Figure A2A)." (PMID 34071557, 2021). "In summary, COVID-19 upregulates both IRAK2 and CHUK, while atherosclerosis only upregulates CHUK, and cardiomyopathy upregulates IRAK2, suggesting that NF-kB activation may be critical in all three conditions." (PMID 34071557, 2021). "Also, while IRAK2 was elevated in monocytes from patients with moderate or severe COVID-19, IRAK3 was only increased in severe COVID-19." (PMID 37310504, 2023).
Helminthic Infection (2 papers, 2011 to 2025). "In studies involving worm infections, IRAK-2 (interleukin-1 receptor-associated kinase-like 2) has been shown to enhance Th17 cell development by augmenting IL-1-induced activation of RORγT and BATF, which may contribute to disease exacerbation." (PMID 39876010, 2025).
lupus (2 papers, 2015 to 2016). "Because the other components of the Myddosome are IRAK1 and IRAK4 and the inactive pseudokinase IRAK2, we studied whether the loss of IRAK1 or IRAK4 catalytic activity, or IRAK2 function, prevented lupus in ABIN1[D485N] mice." (PMID 27807192, 2016).
Oral Cancer (2 papers, 2021 to 2023). "Clinically, 172 stage I-IVB resected oral cancer patients were used to validate IRAK2 expression in predicting clinical outcomes." (PMID 37108068, 2023). "Patient characteristics of 41 oral cancer patients according to the expression level of IRAK2." (PMID 34249686, 2021).
Oral Squamous Cell Carcinoma (2 papers, 2021 to 2023). "This was a retrospective study conducted between IRAK2 expression and the outcomes of oral squamous cell carcinoma patients after radiotherapy treatment." (PMID 37108068, 2023). "A total of 172 I-IVB specimens from oral squamous cell carcinoma patients were collected for clinical analysis, from which IRAK2 expression was analyzed by immunohistochemistry." (PMID 37108068, 2023).
pancreatic cancer (2 papers, 2023 to 2025). "IRAK2 is highly expressed in pancreatic cancer patients and associated with poor prognosis." (PMID 37108068, 2023). "IRAK2 knockdown has led to a significant impairment of pancreatic cancer cell proliferation." (PMID 37108068, 2023).
AIDS (1 paper, 2022). A syndrome resulting from the acquired deficiency of cellular immunity caused by the human immunodeficiency virus (HIV). "We found that all of 3 IRAK isoforms (IRAK1, IRAK2, and IRAK4) we tested were highly expressed in AIDS-KS tissues when compared to those in normal skin tissues." (PMID 36457850, 2022).
Arthritis (1 paper, 2024). Inflammation of a joint. "The difference is that bee venom reduces arthritis damage to bone and cartilage by inhibiting the IRAK2/TAK1/NF-κB signaling pathway, NF-κB signaling pathway, and JAK/STAT signaling pathway, as well as decreasing osteoclastogenesis by inhibiting the RANKL/RANK signaling pathway." (PMID 39591207, 2024).
autoimmune disease (1 paper, 2011). A disorder resulting from loss of function or tissue destruction of an organ or multiple organs, arising from humoral or cellular immune responses of the individual to their own tissue constituents. "The use of wild-derived mice unravels IRAK-2 as a novel regulator of IL-1-induced pathogenic Th17 cells in schistosomiasis, which likely has wide-ranging implications for other chronic inflammatory and autoimmune diseases." (PMID 21998578, 2011). "Our findings thus identify IRAK-2 as a single regulator of pathogenic Th17 cell development in murine schistosomiasis and reveal a novel mechanism that is likely to operate in other chronic inflammatory and autoimmune diseases." (PMID 21998578, 2011).
breast invasive carcinoma (1 paper, 2022). "Meanwhile, a lower expression of IRAK2 was observed in uterine corpus endometrial carcinoma (UCEC), prostate adenocarcinoma (PRAD), lung squamous cell carcinoma (LUSC), breast invasive carcinoma (BRCA), and kidney chromophobe (KICH)." (PMID 35211171, 2022).
cardiomyopathy (1 paper, 2021). A disease of the heart muscle or myocardium proper. "Interestingly, IRAK2, another NF-kB pathway regulator, is upregulated in cardiomyopathy patients." (PMID 34071557, 2021).
colon adenocarcinoma (1 paper, 2022). "IRAK2 was more expressed in rectum adenocarcinoma (READ), colon adenocarcinoma (COAD), esophageal carcinoma (ESCA), stomach adenocarcinoma (STAD), THCA, lung adenocarcinoma (LUAD), liver hepatocellular (LIHC), and kidney renal clear cell carcinoma (KIRC)." (PMID 35211171, 2022).
colon cancer (1 paper, 2020). "Recently, IRAK2 has also been described as a potential tumor suppressor in colon cancer that counterbalances oncogenic Smurf1 by phosphorylation of its threonine residues and promoting its self-degradation by ubiquitylation." (PMID 32841292, 2020).
colorectal cancer (1 paper, 2023). A primary or metastatic malignant neoplasm that affects the colon or rectum. "For example, IRAK2 mediates the phosphorylation of Smurf1, which triggers ER stress-mediated apoptosis in colorectal cancer cells." (PMID 37108068, 2023).
dermatitis (1 paper, 2017). An inflammatory process affecting the skin. "It was of interest to evaluate IMQ dermatitis in MOLF mice, since previous studies have identified MOLF genetic variants impacting Toll-like receptor (TLR) signaling, including alleles associated with Tlr5, Irak1bp1, Irak2, Irak2c, and Cyld." (PMID 28279190, 2017).
epilepsy (1 paper, 2024). A brain disorder characterized by episodes of abnormally increased neuronal discharge resulting in transient episodes of sensory or motor neurological dysfunction, or psychic dysfunction. "IRAK2 was mostly expressed in the G4 group and highly expressed in the G1 epilepsy group." (PMID 39046369, 2024).
gingivitis (1 paper, 2019). A disorder involving inflammation of the gums; may affect surrounding and supporting structures of the teeth. "Besides the upregulation induced by the commensal biofilm, we also found that gingivitis biofilm significantly up-regulated CD14; gingivitis and cariogenic biofilms both up-regulated IRAK2 transcription; while the cariogenic biofilm slightly suppressed CD14, IRAK4, and IRF3 transcription." (PMID 31448244, 2019). "Gingivitis and cariogenic biofilms had little effect on both pathways except for gingivitis biofilm increasing CD14 and both biofilms increasing IRAK2 significantly." (PMID 31448244, 2019). "MyD88, IRAK2, IRAK4 (MyD88-dependent), and TBK1 (MyD88-independent) were significantly up-regulated in RHG exposed to commensal biofilm compared to gingivitis or cariogenic biofilms." (PMID 31448244, 2019).
lymphoma (1 paper, 2021). A malignant (clonal) proliferation of B- lymphocytes or T- lymphocytes which involves the lymph nodes, bone marrow and/or extranodal sites. "In 2020, researchers from the University of North Carolina have validated that IRAK2-associated signaling pathway participates in the initiation and progression of lymphoma primarily triggered by the herpes virus." (PMID 34899868, 2021). "Analytical results indicated that some inferred genes, such as RAC3, TEC, IRAK2/3/4, PRKCE, SMAD3, BLK, TXK, PRKCQ, were associated with the initiation and progression of lymphoma." (PMID 34899868, 2021). "IRAK2 (ENSP00000256458), as the next predicted gene, has been reported to contain multiple significant variants associated with lymphoma through interactions with Toll-like receptors." (PMID 34899868, 2021). "The analytical results showed that some of these genes (RAC3, TEC, IRAK2/3/4, PRKCE, SMAD3, BLK, TXK, PRKCQ) could be novel lymphoma-associated genes." (PMID 34899868, 2021).
mastitis (1 paper, 2022). Inflammation of breast tissue during lactation or postpartum due to an obstructed duct or infection. "The studies indicate that miR-15a constitutes potential miRNA-mRNA regulatory pairs with target gene (IRAK2) for use as biomarkers to predict a mastitis response or indirectly affects the expression of CD163 gene in E. coli-infected mastitis cows." (PMID 35396568, 2022).
neuroborreliosis (1 paper, 2023). "Interestingly, a recent in vitro study of neuroborreliosis, using human brain microvascular endothelial cells challenged with Borrelia bavariensis, also showed an upregulation of IRAK2 and MYD88, while no significant changes were detected for IRAK1 or TRAF6 expression." (PMID 37319241, 2023).
non-small cell lung carcinoma (1 paper, 2023). A group of at least three distinct histological types of lung cancer, including non-small cell squamous cell carcinoma, adenocarcinoma, and large cell carcinoma. "Another previous study showed that the SNP rs779901 T allele genotype in IRAK2 was associated with the increased expression of IRAK2 mRNA in non-small cell lung cancer (NSCLC) patients." (PMID 37108068, 2023).
pituitary adenoma (1 paper, 2010). "Our pituitary adenoma nitroproteomic study has discovered the IL1-IL1R-IRAK2 complex in a human pituitary adenoma tissue; IL-1 was nitrated, and IRAK2 (interleukin-1 receptor-interacting protein 2) was identified to associate with IL1R." (PMID 20426862, 2010).
prostate carcinoma (1 paper, 2023). A carcinoma that arises from epithelial cells of the prostate gland. "Previous studies reported that IRAK2 participates in the UPR in the presence of ER stress in prostate cancer cells; therefore, we wondered if IRAK2 could be involved in the ERN1 signalling pathway in BCSCs." (PMID 36768848, 2023).
psoriasis (1 paper, 2011). An autoimmune condition characterized by red, well-delineated plaques with silvery scales that are usually on the extensor surfaces and scalp. "Another possible target is IRAK2 encoding the interleukin-1 receptor-associated kinase 2 that was reported to participate in the IL1-induced up-regulation of NF-kappaB, a pathway known to be involved in the pathogenesis of psoriasis." (PMID 21687694, 2011).
pulmonary diseases (1 paper, 2022). "Interestingly, IRAK2 and MECOM hub genes from these COPD network clusters are known for their involvement in different pulmonary diseases." (PMID 36194576, 2022).
schistosomiasis (1 paper, 2011). An infectious disease caused by parasitic trematodes of the genus Schistosoma that colonize human blood vessels and release eggs that can cause granulomatous reactions leading to acute (swimmer's itch or acute schistosomiasis syndrome) or chronic disease. "We now demonstrate that a single gene, Irak2, is capable of controlling severe pathology in murine schistosomiasis." (PMID 21998578, 2011).